ESX1 (ESX homeobox 1)
Diseases named in the same sentence as ESX1 in open-access papers (continued):
Sharing a sentence is not in itself a finding about the gene and the disease.
infection (continued). "In light of recent advances in these areas, we re-examined this model and found that its unique features allow a detailed analysis of infection leading to new insights into the biological role of Esx-1, a major virulence determinant generally involved in mycobacterial pathogenesis." (PMID 20463815, 2010). "It remains to be determined whether perturbing host membranes is the only role played by ESX1 during infection, or if this system also serves additional functions analogous to the specialized secretion systems of other pathogens." (PMID 19578435, 2009). "Given that we showed ESX-1 activity contributes to presentation of Mtb antigens in infection with virulent Mtb H37Rv, the fact that BCG and Mtb H37Ra are both deficient in ESX-1 activity may in part explain this difference in the mycobacterial peptides presented on MHC-I." (PMID 37073954, 2023). "Moreover, Mtb-mediated AIM2 inflammasome inhibition is dependent on a functional ESX-1 secretion system since infection with the Mtb strain deficient in esxA fails to inhibit IL-1β secretion induced by Msme." (PMID 35237260, 2022). "Surprisingly, in these infection experiments, CpnT could also not be detected in macrophages infected with the ESX-1-deficient strain." (PMID 33653883, 2021). "We reasoned that if a WT bacterium, containing a functional ESX-1 system, was trapped in the same phagosome with a bacterium lacking this functional system, the WT bacterium would enable the mutant strain to translocate to the host cell cytosol and trigger CpnT secretion during infection." (PMID 33653883, 2021). "Furthermore, because EsxA and EsxB secretion was diminished, other ESX-1 substrates in addition to these central substrates might be involved in the infection process." (PMID 30102741, 2018). "During the first 21 days of infection ΔRD1 lesions also contained more T cells, which localized throughout the entire structure rather than organized to the periphery as in wild type infection, implying that Esx-1 affects T cell functions in vivo via unappreciated mechanisms." (PMID 20463815, 2010). "Analysis of TNFα and IL-6 demonstrated Esx-1-dependent secretion, implying that Esx-1 promotes NFκB activation in macrophages in vitro, which could account for the increased TNFα seen in infections by wild type M. marinum in vivo." (PMID 20463815, 2010). "However, the biological function of Esx-1 during infection remains incompletely understood." (PMID 20463815, 2010). "As much of the work examining ESX-1 function has been conducted in vitro, we lack a clear understanding of all the factors that attenuate ESX-1 mutants during in vivo infection." (PMID 40463021, 2025). "We then investigated if ESX-1 and PDIM suppress IL-23 production by dendritic cells during in vivo infection in the draining (mediastinal) lymph nodes." (PMID 40463021, 2025). "During infection, M. tb secretes numerous virulence factors, including the 6 kDa early secretory antigen target (ESAT-6), which is produced by the ESX-1 secretion system." (PMID 40205554, 2025). "Major pathways involved in the survival of M. marinum during infection of D. discoideum are related to DNA damage repair, lipid and vitamin metabolism, the type VII secretion system (T7SS) ESX-1, and the Mce1 lipid transport system." (PMID 38270456, 2024). "Therefore, ESX-1 may be differentially regulated in the laboratory and during infection." (PMID 38445877, 2024). "This recruitment was significantly attenuated upon infection with M. marinum ∆RD1 that produces PDIMs but lacks a functional ESX-1 secretion system." (PMID 37070811, 2023). "B-cell cellularity remained similar throughout the infection, and CD4+ and CD8+ T lymphocytes increased modestly with a significant contribution of ESX-1." (PMID 37017530, 2023).
infection (continued). "To probe the relationship between Mtb-mediated phagosomal membrane damage and innate immune recognition of infection, we serially profiled the macrophage response to wild-type Mtb or PDIM and ESX-1 Mtb mutants, which fail to damage the phagosomal membrane." (PMID 34755600, 2021). "Our work suggests that the canonical Mtb virulence factors PDIM and ESX-1 function to blunt a distinct, endosome-specific component of the TLR2 response, and that this interference in fact modulates infection outcomes in macrophages and in mice." (PMID 34755600, 2021). "We first confirmed that pre-treatment with concanamycin A, which inhibits the vacuolar ATPase, limits phagosome acidification in BMDM using both zymosan beads and infection with pHrodo-labeled PDIM and ESX-1 mutants." (PMID 34755600, 2021). "Here, we find that ESX-1 mutants and PDIM synthesis and export mutants share a common multiparametric phenotype of infection." (PMID 28505176, 2017). "Ourdata suggest that after infection, the concerned phagocytes may persist in the organslong enough to have a potential impact on host defense mechanisms that likely alsoinclude key cellular processes, such as autophagy, which requires Mtbubiquitination in an ESX-1-dependent manner." (PMID 25658322, 2015). "Of note, infection with wild type M. marinum induced higher levels of pro-caspase-1 than ΔRD1, independent of the inflammasome, which might be explained by secretion of Esat-6, a major Esx-1 substrate that has been proposed to induce caspase-1 gene expression in macrophages." (PMID 20463815, 2010). "The ESX-1 secretion system (early secreted antigen 6 kilodaltons [ESAT-6] system 1) delivers protein virulence factors essential for phagosome lysis, facilitating infection." (PMID 42053305, 2026). "We found that this is independent of duration and route of infection but instead results from an overly robust Th1 response, which suppresses Th17 development, and upon the virulence factors ESX-1 and PDIM." (PMID 40463021, 2025). "Because IL-23 promotes Th17 responses, and ESX-1 and PDIM are responsible for the lack of a Th17 response during Mtb infection, we next investigated if ESX-1 and PDIM suppress IL-23 production in bone-marrow-derived macrophages (BMDMs) during in-vitro infection." (PMID 40463021, 2025). "Analysis over a range of multiplicities of infection further established that the cytosolic serpins do not regulate ESX-1-mediated inflammasome activation in macrophages." (PMID 39087767, 2024). "Previous studies revealed that mycobacterial strains lacking the outer lipid PDIM have impaired ESX-1 function during laboratory growth and infection." (PMID 38661343, 2024). "The fraction of neutrophils that harbored bacteria was similar in WT and ΔRD1 infections, suggesting that ESX-1 did not affect the infectivity rate of recruited cells." (PMID 37017530, 2023). "In contrast to WT Mtb, infection with ΔeccC Mtb resulted in similar levels of Mtb-Lysotracker colocalization in WT and TKO cells, indicating that galectin-dependent lysosomal trafficking requires ESX-1 and cytosolic access." (PMID 37352334, 2023). "Critical role for the ESX-1/EsxA in NLRP3 activation has also been reported during the infection with non-tuberculous mycobacteria species including Mmar, and Mkan." (PMID 35237260, 2022). "As expected, macrophages infected with the ESX-1-deficient strain showed almost no bacteria that were labeled with the FK2 antibody (5.7% of bacteria were Ub+), while in the case of the WT infection, almost half of the bacteria were positive (41%)." (PMID 33653883, 2021). "We next sought to understand whether the interaction between PDIM/ESX-1 and TLR2 contributes to infection outcomes in macrophages." (PMID 34755600, 2021).
infection (continued). "At 6, 12, or 24 hr post-infection, pHrodo mean fluorescent intensity around PDIM- or ESX-1-mutant Mtb was significantly higher than around wild-type Mtb, suggesting that phagosomes containing PDIM- or ESX-1-mutant Mtb becomes relatively more acidic than phagosomes containing wild-type Mtb." (PMID 34755600, 2021). "The Mtb ESX-1 protein secretion system has long been known to mediate phagosomal membrane damage; the mycobacterial lipid PDIM was more recently found to play a similar role in infection." (PMID 34755600, 2021). "As previously demonstrated in BMMs, we observed that many interferon-stimulated genes were more highly induced upon infection with WT M. tuberculosis than M. tuberculosis lacking ESX-1 in both BMMs and CIMs." (PMID 31204998, 2019). "Previous work demonstrated that the MCV suffers continuous ESX-1-dependent insults and injuries during infection, from the first hour post-entry, when no macroscopic sign of breakage is observed, until about 24 hpi, when the bacteria escape to the cytosol." (PMID 30596802, 2018). "We conclude that, early after infection of D. discoideum, M. marinum induces autophagosome formation presumably via downregulation of TORC1, which might be dependent on the activity of the ESX-1 secretion system." (PMID 28414774, 2017). "At the early stages of infection, Mtb has not been observed to localize in the cytosol in mouse macrophages, but time-dependent phagosomal membrane damage via ESX-1 and release of bacterial DNA has been reported." (PMID 28494243, 2017). "Alternatively is ESX-1 secretion during a human infection not critically dependent on the same proteins that have been found to be important for ESX-1 secretion in mice." (PMID 28436493, 2017). "By examining infection at later time points, we found that ESX-1 mutant granulomas did not become necrotic, unlike their wild-type counterparts." (PMID 26159717, 2015). "The role of RD1, and hence ESX1, in early cellular aggregation and local spread of infection has not hitherto been tested in M. tuberculosis in humans." (PMID 24631198, 2014). "In contrast, our findings indicated that secretion of this cytokine is enhanced by infection with Esx-1-proficient bacteria both in vivo and in non-primed macrophages in vitro." (PMID 20463815, 2010). "No induction in Rip2 polyubiquitination was observed upon infection with a strain of Mtb harboring the “RD1” mutation, which deletes a portion of the ESX1 locus." (PMID 19578435, 2009). "As with ESX-1 mutant infections, PRZ treatment did not restore bacterial cording of ESAT-6 mutants." (PMID 36103894, 2022). "Other attenuated Mtb strain, presently in preclinical development with promising results in murine infection models, is the MtbΔppe25-pe19 strain, in which selected PE and PPE proteins of the ESX-5 secretion system have been deleted, but which retains an intact ESX-1 secretion system." (PMID 29218036, 2017). "While it is not surprising that they share similar characteristics of attenuation within infected macrophages, remarkably, they also both failed to induce the macrophage type I IFN response upon infection—a phenotype previously attributed solely to ESX-1 mutants." (PMID 28505176, 2017). "This apparent paradox might be explained by in vivo contribution from dendritic cells, whose secretion of IL-12p40 is not repressed by infection with Esx-1-proficient M. tuberculosis." (PMID 20463815, 2010). "Despite these similarities, the role played by ESX1 during infection remains unclear, since no translocated effectors have been identified to date." (PMID 19578435, 2009). "While differential recruitment may partially be explained by an overall lower bacterial burden and altered infection dynamics with an ESX-1 mutant, in the experiment for BMDM harboring a similar burden of wild-type or RD1 strain, scRNA-seq data demonstrated ESX-1–dependent responses." (PMID 39813329, 2025).
infection (continued). "The data also reveal that the strains examined differ in their ESX-1- (type VII) but not SecA (type I)-mediated protein secretion activity, which correlates with enhanced spread, suggesting that Esx-1 may contribute to nonlytic spread of M. tuberculosis in the early stages of infection in the lungs." (PMID 35695454, 2022). "Notably, M. tuberculosis phoP mutants display pleiotropic phenotypic effects including impaired secretion of ESX-1 substrates, compromised production of sulphatides (SL), diacyltrehaloses (DAT) and polyacyltrehaloses (PAT) and reduced virulence in the macrophage and mouse models of infection." (PMID 24874799, 2014). "Using aerosol infection, we compared uninfected mice, mice infected with MTB H37Rv, and mice infected with an attenuated H37Rv lacking functional ESX-1 machinery." (PMID 39813329, 2025). "To delve further into transcriptional differences between infection states, we directly compared BMDM infected with H37Rv with and without functional ESX-1." (PMID 39813329, 2025). "Mpt64 did not colocalize with the ER after infection with a Mtb type VII secretion system mutant, underscoring the importance of the phagosome-disrupting properties of the ESX-1 system in establishing communication with the host cell." (PMID 31167949, 2019). "Given that ESX-1 and PDIM mutants elicit type I IFN, and type I IFN suppresses Th17 cells, it is perhaps surprising that type I IFN does not explain the suppression of Th17 we observe during early infection." (PMID 40463021, 2025). "Infection with the pckA mutant did not elicit enhanced expression of subcluster 1B genes, demonstrating that the enhanced response to PDIM or ESX-1 mutants is not a general response to mutants with impaired intracellular survival." (PMID 34755600, 2021). "However, ubiquitination and non-autophagic sequestration may occur later during infection with M. tuberculosis, since there is evidence that after two days it escapes to the cytosol of human monocyte-derived dendritic cells and macrophages through an ESX-1 dependent mechanism." (PMID 19436699, 2009).
cancer (1 paper, 2017). A tumor composed of atypical neoplastic, often pleomorphic cells that invade other tissues. "Some of the TFs that were downregulated in NLPs, including Esx1, Bhlhe41, and Dmrt1, have been reported to play critical roles in negatively regulating cancer cell and stem cell growth in other tissues." (PMID 28725177, 2017).
ESX1 also shares sentences with these, for which no sentence is quoted: tumor (2 papers); bacterial infection (1); breast carcinoma (1); growth disorders (1); Infertility (1); pituitary hormone deficiencies (1); psoriasis (1); seminoma (1); Simpson-Golabi-Behmel syndrome (1); skeletal tuberculosis (1); subependymoma (1).